TREM1 (triggering receptor expressed on myeloid cells 1)
Diseases named in the same sentence as TREM1 in open-access papers (continued):
Sharing a sentence is not in itself a finding about the gene and the disease.
glioma (continued). "Correlation of TREM1 expression in human glioma patients with clinicopathological features." (PMID 32765489, 2020). "TREM1 might be a predictive marker for glioma immunotherapy." (PMID 38370418, 2024). "Therefore, TREM1 may be a novel and attractive immune target and may exhibit new avenues to overcome the low response rate of glioma patients to current immunotherapies." (PMID 38370418, 2024). "Moreover, gene ontology and KEGG analyses showed that TREM1 might play a role in immunologic biological processes in glioma." (PMID 38370418, 2024). "Importantly, TREM1 was a valuable independent prognostic factor in glioma." (PMID 38370418, 2024). "Our study highlights that TREM1 modulates the TLR4/PI3K/AKT/mTOR signaling axis to regulate biological functions and the PMT process in glioma cells." (PMID 41394801, 2025). "TREM1 shows significant enrichment in aggressive GBM subtypes and its inhibition functionally mediates anti-tumor effects by suppressing the glioma proneural-to-mesenchymal transition through modulation of the TLR4/PI3K/AKT/mTOR pathway." (PMID 41394801, 2025). "TREM1 was enriched in the mesenchymal subtype and significantly upregulated in IDH wild-type glioma." (PMID 38370418, 2024). "Gliomas are classified into five types in the 2016 WHO CNS tumor classification, LGG-Oligo had the lowest TREM1 expression, while GBM IDHwt showed the highest expression." (PMID 38370418, 2024). "In vitro biological and functional assays showed that increased expression of TREM1 enhanced chemotaxis of monocytes and altered TAM composition in the TME of glioma." (PMID 38370418, 2024). "Our results demonstrated that TREM1 was highly expressed in GBM and was a valuable prognostic biomarker for glioma patients." (PMID 38370418, 2024). "Chemotaxis of neutrophils and Mφ towards glioma cells is attenuated by the inhibitor of HuR dimerization SRI42127 and the TREM1-decoy peptide LP17 in vitro." (PMID 36249290, 2022). "In our cohort of glioma patients, we found that the serum levels of HMGB1 negatively correlated with the percentage of TREM-1+ Mo and with the TREM-1/TREM-2 ratio." (PMID 32684831, 2020). "This characteristic elucidated the underlying reason for the enrichment of immune activation in the TREM1-high subgroup, without hindering glioma progression." (PMID 38370418, 2024). "In both the TCGA and CGGA datasets, TREM1 expression was found to be positively correlated with HCK, interferon, LCK, MHC-I, MHC-II, and STAT1 metagenes but negatively correlated with IgG metagenes in glioma." (PMID 38370418, 2024). "Triggering receptor expressed on myeloid cells 1 (TREM1), which belongs to the Ig-like superfamily expressed on myeloid cells, is reportedly involved in various diseases but has rarely been studied in glioma." (PMID 38370418, 2024). "We found a negative correlation of the serum levels of HMGB1 in glioma patients with both percentages of CD14+ TREM-1+ cells (P = 0.049) and TREM-1/TREM-2 ratio (P = 0.004)." (PMID 32684831, 2020). "Following this, they developed a nomogram utilizing the TREM1 expression level, WHO grade, gender, age, radiotherapy, chemotherapy, and IDH status, sourced from the TCGA cohort, to forecast the 1-year, 3-year, and 5-year survival probabilities of glioma patients." (PMID 40599767, 2025). "Furthermore, we did not systematically investigate the detailed mechanisms of TREM1 regulating the immune microenvironment and promoting the efficacy of immunotherapy in glioma, which we will focus on studying in future studies." (PMID 38370418, 2024). "However, they found no significant changes when they compared TREM-1 levels on monocytes between glioma grades and between gliomas and healthy patients." (PMID 35875168, 2022). "In all glioma patients, we observed a positive correlation of percentage of CD14+ TREM-1+ cells with the IL-6/IL-10 ratio (P = 0.007) and a negative correlation with the plasma levels of IL-10 (P < 0.0001)." (PMID 32684831, 2020).
periodontitis (14 papers, 2013 to 2025). An acute or chronic inflammatory process that affects the tissues that surround and support the teeth. "In RA, periodontitis was associated with increased TREM-1 and PGLYRP1 levels (p < 0.05), yet in patients under methotrexate TREM-1 levels were lower." (PMID 33536478, 2021). "Our present study shows for the first time that TREM-1 regulates alveolar bone loss in experimental periodontitis and paves the way for a novel approach to treat human periodontitis." (PMID 31581596, 2019). "To determine whether there was a cause-and-effect relationship between gingival TREM-1 expression and alveolar bone loss, we subjected groups of mice to ligature-induced periodontitis with local administration of the LP17 or with PBS sham control." (PMID 31581596, 2019). "Thus, our study lends further support to the concept that IL-17 is a key driver of periodontal bone loss, although this is the first time that TREM-1 signaling is linked to IL-17 in the context of periodontitis." (PMID 31581596, 2019). "Importantly, our findings also reveal a previously unidentified TREM-1-driven axis for inflammatory bone loss that could be targeted via small-molecule antagonists for therapeutic intervention in human periodontitis." (PMID 31581596, 2019). "The newly identified STAT3-HIF1α-IL1β signaling pathway, acting downstream of TREM-1, plays a key role in regulating M1 polarization in periodontitis." (PMID 41226426, 2025). "Studies have demonstrated that TREM-1 is expressed in various biological fluids and tissues of individuals with periodontitis, including saliva, serum, gingival tissues, and gingival crevicular fluid." (PMID 41226426, 2025). "In periodontitis, the macrophage M1/M2 ratio significantly increases, while TREM-1 inhibition primarily suppresses M1 polarization." (PMID 41226426, 2025). "In vivo studies using a murine model of periodontitis have highlighted the critical role of TREM-1 in alveolar bone resorption." (PMID 41226426, 2025). "The role of TREM1-mediated neutrophil pyroptosis on periodontitis pathogenicity should be thoroughly investigated." (PMID 36686646, 2022). "This study revealed the upregulation of TREM1 in neutrophil infiltrated in periodontal tissue during periodontitis." (PMID 36686646, 2022). "PGLYRP1 functions as a ligand that activates TREM-1 during illness, so the high values of this biomarker indicate that the patient is probably suffering from systematic inflammation due to periodontitis." (PMID 35225864, 2022). "In this regard, higher levels of salivary TREM-1 and PGLYRP1 were associated with poorer oral health in chronic kidney disease patients with concomitant periodontitis, and a positive correlation was found between salivary TREM-1 and PGLYRP1 levels." (PMID 33536478, 2021). "In our mediation model, the increased TREM-1 concentration found in RA statistically appeared directly mediated by the presence of concurrent periodontitis." (PMID 33536478, 2021). "The mediation analyses showed that serum TREM-1 levels were directly mediated by the presence of periodontitis (B = 52.7259, p = 0.0262) and indirectly mediated via PGLYRP1 serum levels in patients with RA (B = 0.1840, p = 0.0005)." (PMID 33536478, 2021). "Specifically, the presence or expression of TREM-1 is increased in saliva, serum, gingival crevicular fluid, and gingival tissues of patients with periodontitis as compared to individuals with periodontal health." (PMID 31581596, 2019). "The present study conclusively demonstrated the involvement of TREM-1 in alveolar bone resorption during the course of experimental periodontitis in mice." (PMID 31581596, 2019). "The aim of this study was to elucidate the role of TREM-1 using the murine ligature-induced periodontitis model." (PMID 31581596, 2019). "Using the ligature-induced murine periodontitis model, we first investigated the regulation of TREM-1 expression in the gingival tissue." (PMID 31581596, 2019).
periodontitis (continued). "Given that chronic periodontitis is characterized by alternate periods of exacerbation and quiescence, the impaired TREM-1 expression and the inhibited innate immune response would have a significant influence on the periodontal disease progress." (PMID 23977160, 2013). "However, in a ligature-induced periodontitis model, TREM-1 activation increased the RANKL/OPG ratio, potentially through the upregulation of IL-17A." (PMID 41226426, 2025). "Investigate whether serum levels of TREM‐1 and PGLYRP1 are associated with periodontitis in patients with RA." (PMID 39811802, 2025). "The role of TREM1 in liver-related diseases and periodontitis has been extensively studied." (PMID 39563244, 2024). "There is clinical evidence implicating TREM-1 in the pathogenesis of periodontitis." (PMID 31581596, 2019). "However, there are as-yet no interventional studies in preclinical models to conclusively demonstrate TREM-1 involvement in periodontitis." (PMID 31581596, 2019). "Elevated oral and systemic levels of soluble TREM-1 has been found in periodontitis." (PMID 23977160, 2013). "On an indicative basis, these associations between periodontitis, TREM-1 and PGLYRP1 levels were not significant in HC and BD groups (p > 0.05), although a similar trend could be observed in HC participants." (PMID 33536478, 2021). "The major novel finding of this in vivo study is that local (gingival) injection of a TREM-1 blocking peptide, namely LP17, substantially reduced the RANKL/OPG osteoclastogenic ratio and alveolar bone loss, thus providing preclinical support for a new therapeutic target for periodontitis." (PMID 31581596, 2019). "The results revealed an increased proportion of TREM1+ Mφ, characterized by the high IL1B expression, in periodontitis, eosinophilic esophagitis (EoE), IBD, and perianal fistulizing Crohn’s disease (Perianal-CD)." (PMID 41318555, 2025). "The TREM-1-PGLYRP1-IL1β signaling pathway becomes activated in response to bacterial biofilm formation and its removal in periodontitis." (PMID 41226426, 2025). "This is the first bioinformatics report describing the upregulation of necroptosis (IL-1B), pyroptosis IL-1B, TREM1, and FPR2, and ferroptosis (SLC2A3) related genes mainly in human periodontium infiltrated neutrophils during periodontitis." (PMID 36686646, 2022). "We found that among 21 DCDEGs, SLC2A3, FPR2, TREM1, and IL1B were mainly upregulated in neutrophils present in the periodontium of periodontitis patients." (PMID 36686646, 2022). "The scRNA sequencing data analysis revealed that among 21 DCDEGs, SLC2A3, FPR2, TREM1, and IL1B were mainly upregulated in neutrophils present in the periodontium of periodontitis patients." (PMID 36686646, 2022). "Discussion: The findings provide upregulated SLC2A3, FPR2, TREM1, and IL1B in neutrophils as a future research direction on the mode and mechanism of cell death in periodontitis and their role in disease pathogenicity." (PMID 36686646, 2022). "The rigorous bioinformatics analysis performed in this study provided hints that SLC2A3, FPR2, TREM1, and IL1B are upregulated in neutrophils infiltrated in periodontium during periodontitis and mainly attributed to necroptosis, pyroptosis, and ferroptosis." (PMID 36686646, 2022). "In conclusion, our study showed that SLC2A3, FPR2, TREM1, and IL1B mainly upregulated in neutrophils infiltrated in periodontium during periodontitis." (PMID 36686646, 2022). "Elevated TREM-1 levels were observed in saliva, serum and gingival crevicular fluids (GCF) in patients with periodontitis, and TREM-1 serum and saliva levels correlated positively." (PMID 33536478, 2021). "In contrast, the lowest levels of TREM-1 (111.6 ± 53.6 pg/ml) and PGLYRP1 (86.6 ± 52.3 pg/ml) were observed in MTX-treated patients devoid of periodontitis." (PMID 33536478, 2021).
periodontitis (continued). "Both serum TREM-1 and PGLYRP1 levels were increased in RA patients with periodontitis compared to RA patients with healthy periodontium, supporting a potentiating effect of periodontitis towards RA disease activity and inflammation." (PMID 33536478, 2021). "We further analyzed serum levels of TREM-1 and PGLYRP1 in relation to both MTX use and diagnosis of periodontitis." (PMID 33536478, 2021). "TREM-1 and PGLYRP1 levels in various biofluids are elevated in periodontitis patients compared to periodontally-healthy controls." (PMID 33536478, 2021). "The present study aimed to investigate potential associations that exist in RA patients between serum levels of TREM-1, its ligand PGLYRP1, periodontitis and indicators of RA disease activity." (PMID 33536478, 2021). "Increased serum TREM-1 levels correlated with PGLYRP1, CRP and DAS-28-ESR in RA patients with periodontitis." (PMID 33536478, 2021). "Moreover, the cell proportion of pyroptotic epithelial cells was elevated in periodontitis, EoE, IBD, and perianal-CD, with heightened intercellular communication with TREM1+ Mφ, except in EoE." (PMID 41318555, 2025). "The highest serum levels of TREM-1 (244.2 ± 119.2 pg/ml) and PGLYRP1 (317.8 ± 390.6 pg/ml) were observed in non-MTX patients affected by periodontitis." (PMID 33536478, 2021). "RA patients diagnosed with periodontitis displayed significantly higher TREM-1 and PGLYRP1 levels as compared to patients without periodontitis (TREM-1; p = 0.001 and PGLYRP1; p = 0.037)." (PMID 33536478, 2021).
lupus (13 papers, 2016 to 2025). "Although TREM-1 deficiency has been shown to exhibit reduced renal pathology, conversely, TREM-1 deficiency exacerbates the disease activity of microbial-induced sepsis, liver abscesses, and lupus." (PMID 31189465, 2019). "miRNA-150 is a critical immune regulator, for instance driving expression of the inflammatory receptor TREM-1 (Triggering receptor expressed on myeloid cells 1) in dendritic cells and contributing to lupus-like symptoms in mice." (PMID 36324510, 2022). "Our immunohistochemistry studies in murine and human lupus renal samples indicate that TREM-1 can be expressed by the inflammatory infiltrate and renal epithelial cells in chronic disease (manuscript in preparation)." (PMID 27083877, 2016). "Moreover, miR-150 upregulation inhibited TREM-1 expression in splenic conventional dendritic cells and mitigated the inflammatory response in systemic lupus erythematosus." (PMID 36681676, 2023). "Other downregulated pathways included “phosphoinositide 3–kinase (PI3K) signaling in B-lymphocytes”, “ribosomal protein S6 kinase beta 1 (p70S6K) signaling”, and “triggering receptor expressed on myeloid cells 1 (TREM1) signaling systemic lupus erythematosus in B-cell-signaling pathway”." (PMID 36900319, 2023). "While NETosis is induced by various stimuli including IFN-α, our data might indicate that TREM-1 potentiates NET release in lupus patients with high serum MPO-DNA levels as observed in sepsis." (PMID 36319843, 2022). "Triggering receptor expressed on myeloid cells-1 (TREM-1) might play a part in the pathogenesis of autoimmune disorders such as lupus through TLR-induced inflammatory responses." (PMID 34394079, 2021). "In summary, we showed in the current study that autophagy was increased in lupus-prone TREM-1−/−." (PMID 32462028, 2020). "To understand whether autophagy plays a role in lupus, we compared autophagy levels in lupus-prone B6.lpr and TREM-1−/−." (PMID 32462028, 2020). "Trem1−/− mice with lupus-prone backgrounds exhibited elevated serum BAFF, anti-dsDNA antibody levels, expanded lymphocyte populations, and increased renal immune complex deposition, leading to severe lupus symptoms and higher mortality." (PMID 41226426, 2025).
Obesity (13 papers, 2019 to 2025). Accumulation of substantial excess body fat. "TREM1 has also been shown to be associated with obesity, diabetes, cardiovascular disease, cancer, and incident dementia." (PMID 37697678, 2023). "TREM-1 has been found to be overexpressed in patients with obesity, predisposing pre-diabetics to obesity-induced insulin resistance." (PMID 31212707, 2019). "Moreover, TREM-1 has been previously associated with inflammation in obesity, insulin resistance and other obesity-associated comorbidities." (PMID 37626613, 2023). "Our hypothesis is that TREM-1 plays a major role in the generation and perpetuation of inflammation during obesity and its associated complication (Insulin resistance and cardiac dysfunction)." (PMID 36699032, 2022). "Interestingly, a recent report has demonstrated that overexpression of TREM-1 in the liver and M1 hepatic macrophages polarization were associated with obesity-induced insulin resistance (IR)." (PMID 32195263, 2020). "Also, only limited studies linked TREM-1 or uPAR with obesity." (PMID 40003433, 2025). "In one study, TREM-1 was shown to be raised significantly in blood and tissue biopsies from obese subjects, suggesting a possible role in obesity pathophysiology." (PMID 40003433, 2025). "In the mouse model of high-fat diet-induced obesity, we found that Trem1 suppression limited weight gain, insulin resistance and inflammation in white adipose tissue and liver." (PMID 36699032, 2022). "Having demonstrated the expression and functionality of TREM-1 in adipose cells, we moved to the classical diet-induced obesity model in mice." (PMID 36699032, 2022). "Anyway, TREM-1 activation seems to have a role in diet-induced obesity in mice by reducing weight gain, liver inflammation and protecting against associated comorbidities such as insulin resistance and cardiac dysfunction." (PMID 36699032, 2022). "To get more insights into the role of TREM-1 in obesity, we submitted mice to a high-fat diet and investigated the effects of the genetic Trem1 deletion on obesity development and its consequences." (PMID 36699032, 2022). "However, the less reported obesity biomarkers include the Triggering Receptors Expressed on Myeloid cells-1 (TREM-1), which is an immunoglobulin (Ig) superfamily transmembrane protein in humans." (PMID 40003433, 2025). "TREM1 overexpression was also related to insulin resistance induced by obesity." (PMID 34221733, 2021). "A study pointed out that sTREM1 expression was significantly higher in patients with obesity and diabetes than those with only obesity or without obesity and diabetes, which points to the important role of TREM1 in the potential pathophysiology of obesity and diabetes." (PMID 34221733, 2021). "Moreover, recent studies have demonstrated that TREM-1 mediated signaling modulation of M1 macrophage activation promoted the inflammatory response in alcoholic liver disease and obesity-induced fatty liver disease." (PMID 32195263, 2020). "For the other examined inflammatory biomarkers, the plasma IL-8, PCT, TREM-1, and uPAR concentrations were not correlated with BMI or body weight nor associated with obesity, as the levels of these biomarkers were comparable between obese and non-obese groups, and in all four classes of obesity." (PMID 40003433, 2025). "Moreover, it is necessary to determine whether Trem1 deletion could provide long-term protection for mice from the development of obesity-related comorbidities." (PMID 36699032, 2022). "We observed that the genetic ablation of Trem1 dampened HFD-induced weight gain, inflammation, and insulin resistance, hallmarks of obesity." (PMID 36699032, 2022). "In this context, the increase in TREM-1 expression compared to non-obese patients suggests an inflammatory activity by neutrophils, while patients with obesity were under mean longer treatment with corticosteroids." (PMID 37626613, 2023).